POSTN (periostin)
Diseases named in the same sentence as POSTN in open-access papers (continued):
Sharing a sentence is not in itself a finding about the gene and the disease.
lymphoma (3 papers, 2018 to 2020). A malignant (clonal) proliferation of B- lymphocytes or T- lymphocytes which involves the lymph nodes, bone marrow and/or extranodal sites. "Given the sizes of the ß-coefficients of the extracellular matrix proteins lumican and periostin in the 8-protein regression equation, intra-lymphoma variability in extracellular matrix may significantly affect the GCB score." (PMID 32398793, 2020).
metabolic syndrome (3 papers, 2016 to 2025). A cluster of metabolic risk factors for CARDIOVASCULAR DISEASES and TYPE 2 DIABETES MELLITUS. "POSTN and metabolic syndrome are characterized by inflammation, and an association between POSTN and metabolic syndrome has also been identified." (PMID 38020106, 2023). "A mouse study exploring the role of periostin in heart disease demonstrated that in wild-type mice, a high-fat diet designed to induce metabolic syndrome significantly increased periostin levels along with aortic valve thickening, fibrosis, and MMP-2 and MMP-13 expression." (PMID 40227326, 2025).
mycosis fungoides (3 papers, 2019 to 2022). Classical mycosis fungoides is the most common type of mycosis fungoides (MF), a form of cutaneous T-cell lymphoma, and is characterized by slow progression from patches to more infiltrated plaques and eventually to tumors. "POSTN could even be a biomarker for the progression of Mycosis fungoides, the most common subset of CTCL, as it is expressed in the dermis in the early stage." (PMID 35409404, 2022).
pancreatic adenocarcinoma (3 papers, 2007 to 2024). "Hence, increased periostin expression was only nearly significant in pancreatic adenocarcinoma (656 ± 819 vs 9.1 ± 6.9 for normal pancreas, P = 0.06)." (PMID 18086302, 2007).
pancreatitis (3 papers, 2016 to 2022). Inflammation of the pancreas. "In human PDAC samples, POSTN‐expressing CAFs were observed in pancreatitis areas adjacent to tumors." (PMID 36102377, 2022). "Using IHC, we showed that, in addition to being expressed at the invading front of tumors, POSTN expression was also found in peritumoral pancreatitis area in human tumors and surrounding preneoplastic lesions (ADMs and PanINs) in genetically engineered KPC mouse models." (PMID 36102377, 2022). "Although the functions of UBIAD1 and MK-4 in the pancreas are not clear, periostin, a member of a vitamin K-dependent γ-carboxylated protein family, is reported to be involved in pancreatitis." (PMID 31013667, 2019). "Importantly, expression of three of the five genes, POSTN, SERPINB5 and TMPRSS4, apparently increases gradually from healthy pancreas to pancreatitis and further rises between pancreatitis and PDAC." (PMID 26993610, 2016). "The degree of upregulation when compared to normal tissue was significantly higher in three (POSTN, SERPINB5, TMPRSS4) of five genes than compared to pancreatitis, suggesting that POSTN, SERPINB5 and TMPRSS4 expression increase gradually from healthy pancreas to pancreatitis to PDAC." (PMID 26993610, 2016).
polycystic ovary syndrome (3 papers, 2020 to 2024). A disorder that manifests as multiple cysts on the ovaries. "In this prospective case-control study, we aimed to investigate serum periostin levels and their relationship with metabolic parameters in patients with polycystic ovary syndrome." (PMID 39045965, 2024). "Correlation between periostin level and laboratory parameters in polycystic ovary syndrome patients." (PMID 39045965, 2024). "Periostin levels were significantly higher in patients with polycystic ovary syndrome compared with the control group (4.67±2.46 vs. 2.60±1.41 ng/mL, respectively; p=0.000)." (PMID 39045965, 2024). "Our study revealed a significant elevation in periostin levels among polycystic ovary syndrome patients compared with controls." (PMID 39045965, 2024).
thyroid tumor (3 papers, 2017 to 2024). A benign or malignant neoplasm affecting the thyroid gland. "Recent research indicates that periostin, derived from cancer-associated fibroblasts, enhances thyroid tumor growth by activating FAK-STAT3 signaling." (PMID 39335579, 2024). "We further conducted an integrated analysis of 571 samples (59 normal thyroid, 512 thyroid tumors) from the GEPIA database and also found a significant increase of POSTN expression in human thyroid tumors relative to normal thyroid tissues." (PMID 38773979, 2024). "Periostin (PN) epithelial and stromal overexpression in tumor pathology has been studied according to tumor growth, angiogenesis, invasiveness, and metastasis, but a limited number of studies address PN in thyroid tumors." (PMID 29435461, 2017).
ulcerative colitis (3 papers, 2016 to 2025). An inflammatory bowel disease involving the mucosal surface of the large intestine and rectum. "Periostin expression was determined in colon tissue samples from ulcerative colitis (UC) patients." (PMID 26890265, 2016). "In an RNA sequencing profile comparing colonic mesenchyme between healthy and ulcerative colitis mice, glial cells were typically clustered by the expression of their markers S100B and GFAP, and possible additional markers include Hapln1 and POSTN." (PMID 37551711, 2024).
valvular heart disease (3 papers, 2011 to 2015). "Recent studies have suggested an important role for periostin and transforming growth factor beta (TGFβ) and bone morphogenetic protein (BMP) ligands in heart valve formation and valvular heart diseases." (PMID 21805020, 2011).
acute pancreatitis (2 papers, 2019 to 2022). An acute inflammatory process that leads to necrosis of the pancreatic parenchyma. "However, in periostin-deficient mice, the most striking phenotype of periostin-knockout mice is the replacement of acinar cells by adipocytes after induction of acute pancreatitis." (PMID 31013667, 2019). "In normal mice, periostin expression is strongly induced throughout the fibrotic reaction in cerulein-mediated acute pancreatitis." (PMID 31013667, 2019). "In pancreatic diseases, POSTN is involved in pancreatic regeneration after acute pancreatitis." (PMID 36102377, 2022).
adenoma (2 papers, 2019 to 2023). A neoplasm arising from the epithelium. "In the cancer-adenoma comparison, upregulation of DEGs involved in cell invasion/migration (POSTN, SPP1) and downregulation of DEGs involved in Paneth differentiation (DEFA5/6) were observed." (PMID 31211760, 2019).
anaplastic thyroid cancer (2 papers, 2022 to 2024). "Periostin (POSTN) encoded a secreted extracellular matrix protein and is found to exhibit stromal deposition in invasive portions and cytoplasmic expression of undifferentiated thyroid carcinoma cells." (PMID 36120433, 2022).
ankylosing spondylitis (2 papers, 2021 to 2025). An autoimmune chronic inflammatory disorder characterized by inflammation in the vertebral joints of the spine and sacroiliac joints. "Similarity, in human ankylosing spondylitis, a chronic inflammatory disease, Periostin is downregulated and associated with the Wnt pathway." (PMID 34591063, 2021). "Significant periostin reductions were observed in studies investigating ankylosing spondylitis and dermatomyositis." (PMID 40053143, 2025).
Anxiety (2 papers, 2016 to 2023). Intense feelings of nervousness, tension, or panic often arise in response to interpersonal stresses. "In mice, for instance, periostin has been linked to the development of anxiety-like behavior due to its activation of immune cells." (PMID 37375593, 2023). "Higher levels of periostin have been associated with more severe symptoms of depression and anxiety." (PMID 37375593, 2023). "Scientists have found that people with major depression or anxiety have more periostin in their blood than most people." (PMID 37375593, 2023). "We used a model of stress-induced depression and anxiety in mice to assess the potential antidepressant and anxiolytic effects of vitamins C and D. The correlation between the observed behavior and blood levels of NOx, periostin, and FKBPL was also examined." (PMID 37375593, 2023). "Subjects in cluster B (older, sinonasal disease) have the highest median age, more symptoms of anxiety and depression (highest median HAD score, 12-27), more nasal symptoms (highest Sino-Nasal Outcome Test 20 score), and high levels of serum periostin and sputum MMP3." (PMID 26851968, 2016).
atrial fibrillation (2 papers, 2022). A disorder characterized by an electrocardiographic finding of a supraventricular arrhythmia characterized by the replacement of consistent P waves by rapid oscillations or fibrillatory waves that vary in size, shape and timing and are accompanied by an irregular ventricular response. "Our study also found a strong positive association between atrial fibrillation and the admission level of periostin." (PMID 36010292, 2022). "In multivariate analysis, we found positive associations between admission level of periostin and atrial fibrillation, admission white blood cell (WBC) count, neutrophile–lymphocyte ratio (NLR), creatinine, C-reactive protein (CRP), and glucose level." (PMID 36010292, 2022). "A recent examination of atrial appendages from atrial fibrillation (AF) patients suggested a clear association between periostin levels of atrial tissues and deteriorated heart failure, as well as lessened ejection fraction." (PMID 36611844, 2022).
bladder urothelial carcinoma (2 papers, 2022 to 2023). "Using 20 transurethral resection specimens of bladder urothelial carcinomas, we provisionally analyzed periostin expression by immunohistochemistry and “moderate” but focal epithelial expression was detected in 2 cases (data not shown)." (PMID 35850759, 2022). "In these latter, high levels of POSTN are usually associated with a more aggressive tumor behavior, tumor advanced stages, and poor prognosis, while in human bladder urothelial carcinoma (BUC), unlike in most tumors, POSTN expression seems to be downregulated." (PMID 38076555, 2023). "However, few reports have investigated periostin expression in urothelial carcinoma of the urinary bladder, and the results remain controversial." (PMID 35850759, 2022).
bone tumor (2 papers, 2018 to 2021). "Periostin expression was also prominent in areas of reactive host bone around infiltrating primary and secondary bone tumours, suggesting a role for this matricellular protein in tumour progression." (PMID 30202513, 2018). "There were similarities in the pattern of periostin expression in inflamed RA synovium and growing bone tumours." (PMID 30202513, 2018). "Periostin was also noted in other bone tumours and was found in areas of reactive bone and increased vascularity at the edge of growing tumours, consistent with its involvement in tissue remodelling and angiogenesis associated with tumour progression." (PMID 30202513, 2018). "We therefore tested whether depletion of POSTN would suppress the bone metastasis capability of PCa cells in the orthotopic bone tumor model by implantation of tumor cells into tibia of mice." (PMID 35087756, 2021). "To determine the expression of periostin in primary bone tumours and to assess whether it plays a role in tumour progression, we carried out immunohistochemistry and ELISA for periostin in a range of neoplastic and non-neoplastic bone and joint lesions." (PMID 30202513, 2018). "Our aims were two-fold: first, to determine whether periostin expression is increased in specific bone tumour types; and second, to examine whether periostin plays a role in tumour progression." (PMID 30202513, 2018). "We consistently noted increased expression of periostin in non-lesional bone at the edge of growing benign and malignant bone tumours." (PMID 30202513, 2018). "Variable focal staining for periostin was seen in cellular and collagenous connective tissue of other bone tumours, including non-ossifying fibroma and undifferentiated pleomorphic sarcoma." (PMID 30202513, 2018). "Focal but less prominent staining for periostin was also noted in cellular and collagenous fibrous tissue of other primary bone tumours including non-ossifying fibroma and undifferentiated pleomorphic sarcoma." (PMID 30202513, 2018).
calcification (2 papers, 2018 to 2024). Process by which organic tissue becomes hardened by the physiologic deposit of calcium salts. "The presence of uremic vascular calcification in the aorta was associated with induction of gene expression of the Wnt target gene and marker of proliferation, cyclinD1; the mediator of canonical Wnt signalling, β-catenin and the matricellular proteins, fibronectin and periostin." (PMID 30075015, 2018). "We showed that fibrosis, pathological gingival calcifications and increased expression of various profibrotic and pro-osteogenic proteins such as POSTN, SPARC and VIM were common findings." (PMID 38664418, 2024).
cardiac interstitial fibrosis (2 papers, 2020 to 2024). "In addition, HFD animals receiving MT showed a significant decrease in relative heart weight and cardiac interstitial fibrosis, but also α-SMA, fibronectin and periostin protein expression as compared with HFD rats treated with vehicle." (PMID 32708095, 2020).
cervical squamous cell carcinoma (2 papers, 2021 to 2023). A squamous cell carcinoma arising from the cervical epithelium. "POSTN + fibroblasts showed high expression levels of several ECM remodeling genes (MMP11, CTHRC1, COL1A1, COL1A2, COL3A1, COL10A1, and COL11A1) and enriched signatures of ECM, which were consistent with the previously reported matrix CAFs (mCAFs) in cervical squamous cell carcinoma (CESC)." (PMID 37833788, 2023).
chondrosarcoma (2 papers, 2018 to 2024). A malignant cartilaginous matrix-producing mesenchymal neoplasm arising from the bone and soft tissue. "In both chondroblastoma and clear cell chondrosarcoma, strong expression of periostin was noted in areas of chondroid matrix formation." (PMID 30202513, 2018). "In clear cell chondrosarcoma, periostin staining was seen in the mineralized osteoid-like matrix covering woven bone and cartilage formed by vacuolated tumor cells." (PMID 30202513, 2018). "AMACR helps differentiate between benign enchondromas and malignant chondrosarcomas, while periostin is present in low-grade chondrosarcomas but not in enchondromas, aiding diagnosis." (PMID 39590345, 2024). "Periostin expression was absent in other cartilage tumours including enchondroma and low/high-grade conventional chondrosarcoma." (PMID 30202513, 2018).
chronic heart failure (2 papers, 2022 to 2025). "In this study, we measured NT-proBNP, a widely utilized and well-validated biomarker of congestive heart failure, and two novel protein markers of fibrosis recently found to be associated with SSc, periostin and galectin-3." (PMID 40743121, 2025).
colorectal tumors (2 papers, 2007 to 2025). "Analysis of six colorectal tumors and three normal colon samples revealed only a 2-fold increase in POSTN expression (P = 0.16)." (PMID 18086302, 2007). "Among the IHC biomarkers expressed in colorectal tumors, FAP, α-SMA, VIM, S100A4, PDGFR-α/β, and POSTN were reported in a general review addressing the question of the significance of CAFs in tumor progression and metastasis." (PMID 41450913, 2025).
craniopharyngioma (2 papers, 2016 to 2018). A benign, partly cystic, epithelial tumor of the sellar region, presumably derived from Rathke pouch epithelium. "Up-regulation of periostin has been shown to regulate EMT in adamantinomatous craniopharyngioma cells through the Akt signaling pathway." (PMID 29774119, 2018). "Upregulated periostin significantly promoted the EMT of adamantinomatous craniopharyngioma cells by activating Akt signaling pathway." (PMID 27034956, 2016). "Additionally, periostin overexpression induced the EMT of adamantinomatous craniopharyngioma cells by activating Akt signaling pathway." (PMID 27034956, 2016).
craniosynostosis (2 papers, 2018 to 2024). Craniosynostosis is defined as the premature fusion of one or more cranial sutures leading to secondary distortion of skull shape resulting in skull deformities with a variable presentation. "Collectively, these findings not only highlighted the efficacy of Periostin overexpression in mitigating craniosynostosis in TWIST1+/− mice but also underscored the critical involvement of the Periostin/BMP1 axis in craniosynostosis." (PMID 38369459, 2024). "In short words, this study revealed Periostin/BMP1 axis’s role in coronary craniosynostosis in TWIST1+/− mice by deeply exploring SMSC proliferation and osteogenic differentiation." (PMID 38369459, 2024). "This insight not only unveiled a novel regulatory axis within the cellular milieu of craniosynostosis but also accentuated the intricate molecular dialogue between Periostin and BMP1." (PMID 38369459, 2024). "This discovery of modulating SMSCs by targeting periostin will help improve future therapeutic interventions for craniosynostosis." (PMID 38369459, 2024). "Periostin can significantly inhibit the proliferation of coronal suture cells to improve craniosynostosis." (PMID 38369459, 2024). "These in vitro and in vivo data have implications for determining the mechanisms of periostin in coronal craniosynostosis of patients with SCS." (PMID 29665811, 2018). "The aberrant proliferation of suture-derived cells that has been shown to contribute greatly to craniosynostosis, we then investigated the ability of periostin to modulate the proliferation of the suture-derived cells." (PMID 29665811, 2018). "We have screened out a series of genes related to skull development and craniosynostosis, noting in particular that periostin was downregulated (superior to 5.8-folds) in craniosynostosis patients, a finding that should acquire much attention." (PMID 29665811, 2018). "We identified that periostin, which is an extracellular matrix protein that plays an important role in both bone and connective tissues, is downregulated in craniosynostosis patients." (PMID 29665811, 2018). "In order to study related molecules in craniosynostosis, we identified the fact that there is a low expression of periostin in the fusion sutures of craniosynostosis patients and Twist1+/− mice." (PMID 29665811, 2018). "Conducting broader population studies, including analyzing samples from patients with craniosynostosis, could better validate the Periostin/BMP1 axis." (PMID 38369459, 2024). "In addition, understanding the specific signal transduction pathways and downstream targets in which Periostin/BMP1 regulates coronary craniosynostosis is a potential direction for further research." (PMID 38369459, 2024). "This study also found that over-expressing periostin improved craniosynostosis in TWIST1+/− mice." (PMID 38369459, 2024). "This suite of data collectively underscored the potent regulatory influence of Periostin overexpression on SMSCs, highlighting its pivotal role in modulating both proliferation and osteogenic differentiation processes within the context of craniosynostosis." (PMID 38369459, 2024). "Therefore, we speculated that periostin may be involved in the development of cranial sutures in Twist1+/− mice and it could be a target for an adjuvant therapy to improve craniosynostosis." (PMID 29665811, 2018). "Therefore, we speculated that periostin may influence the biological behavior of suture-derived cells and ameliorate craniosynostosis in Twist1+/− mice." (PMID 29665811, 2018). "In our quest to decode the molecular intricacies behind craniosynostosis in TWIST1+/− mice, we strategically enhanced Periostin expression via targeted adenoviral-mediated overexpression." (PMID 38369459, 2024). "This study explored the Periostin/BMP1 axis in regulating SMSC proliferation and osteogenic differentiation and revealed its effect on craniosynostosis in TWIST1+/− mice." (PMID 38369459, 2024).